MGMT (O-6-methylguanine-DNA methyltransferase)
Diseases named in the same sentence as MGMT in open-access papers (continued):
Sharing a sentence is not in itself a finding about the gene and the disease.
tumor (continued). "The data also support that the combination of tumors with a high stem cell phenotype and unmethylated MGMT promoters had the most aggressive tumor progression and early death." (PMID 36333778, 2022). "This is partly due to the high level of DNA repair activity of O-6-methylguanine-DNA methyltransferase (MGMT) in tumor cells, which transfers the methyl group to the internal cysteine acceptor residue and reduces the effect of the alkylating agent." (PMID 35684445, 2022). "It has also been established that the MGMT promoter methylation is a valuable predictor for the TMZ response of both the initial tumor and the relapse." (PMID 35563629, 2022). "Here, we produced an acquired TMZ-resistant (TMZ-R) model by performing three cycles of TMZ treatment along with in vivo tumor passage using U87 cells, a MGMT-null GBM cell line." (PMID 36316307, 2022). "The conformity of the MGMT methylation status between the tumor and the corresponding cell culture was high (86%)." (PMID 36115076, 2022). "In their study, the MGMT promoter methylation of the tumor appeared to be a predictive marker for successful treatment with temozolomide only." (PMID 35371528, 2022). "At present, the detection of the MGMT promoter mainly depends on genetic analysis after a tumor operation or biopsy, which is expensive and requires invasive surgery." (PMID 35743511, 2022). "Our study presented evidence that patients with baseline tumor volume ≤32 cm3 who had MGMT methylation lived significantly longer (median 560.5 days vs. 329 days without methylation)." (PMID 36009577, 2022). "O6-methylguanine DNA methyltransferase (MGMT): The MGMT is a DNA rebuilding enzyme that shields the tumor cells from the alkylating agent (induced damage during chemotherapy) by eliminating alkyl groups from the O6 position of the guanine." (PMID 36011048, 2022). "In tumor cells expressing high O6-methylguanine-DNA methyltransferase (MGMT), XAF1 response to TMZ is debilitated." (PMID 35274103, 2022). "The relative abundance of tumor‐infiltrating immune cells was further correlated with clinical data of the patients, such as MGMT methylation state, PFS, or OS (Spearman's correlation)." (PMID 34923780, 2022). "A tumor sample was evaluated positively for the methylation of the MGMT promoter in the case of either a hypermethylated MSP evaluation (M/U > 1) or a positive qMSP evaluation based on the PMR > 100% cut-off values." (PMID 36361838, 2022). "The measures were correlated to histopathology regarding tumor entity, isocitrate dehydrogenase (IDH) and MGMT mutation status." (PMID 36292183, 2022). "During treatment, mutations in the IDH1 and ATRX genes are used to determine the grade and aggressiveness of a tumour, whereas the MGMT status is used to determine if treatment with DNA alkylating agents such as TMZ would be worthwhile." (PMID 35681582, 2022). "Since the introduction of simultaneous radiochemotherapy with temozolomide, an up to 21.5% increased number of patients is seen with tumor recurrence, with a positive correlation to supraventricular tumor location and methylated MGMT status." (PMID 35955454, 2022). "Tumor cells were positive for O-6-methylguanine-DNA methyltransferase (MGMT) and IDH1, with a proliferation activity of 2% for Ki-67." (PMID 35991838, 2022). "Another mechanism of TMZ resistance in GBM patients is represented by unmethylated MGMT promoter tumours, where the enzyme proficiently repairs the chemotherapy-induced DNA damage." (PMID 36619857, 2022). "Under normal circumstances, MGMT protects normal tissues from the damage of alkylating agents, whereas in tumor tissues, it increases resistance to alkylating chemotherapeutics." (PMID 35545654, 2022). "Because of the high inter- and intra-tumor heterogeneity and dynamic transformation of MGMT methylation status, precision medicine is currently of particular therapeutic value." (PMID 34976195, 2022).
tumor (continued). "The absence of MGMT activity leads to a decrease in the ability of tumor cells to restore the damaged DNA sections after the action of chemotherapeutic medication with alkylating agent." (PMID 35625744, 2022). "Several independent prognostic factors were incorporated into the nomograms, namely tumor grade, expression levels of PLK4, IDH mutation status, 1p/19q codeletion status, and the MGMT promoter status." (PMID 36620611, 2022). "Among the subgroups based on gender, tumour grade, and MGMT promoter methylation status, the p values in the training set and validation set were all less than 0.0001." (PMID 35386727, 2022). "The surface of the transporters was paired with cRGD to bind to the avß3 integrin receptors in the MGMT gene of tumor cells." (PMID 35684445, 2022). "In normal tissues, the CpG site in the MGMT promoter region is generally in an un-methylated state, but with the occurrence of a tumor, the promoter region is methylated." (PMID 36614997, 2022). "Within the homogenous cohort of 24 IDH1/2wt patients older than 50 years with performed surgical resection of the tumor mass, 10 patients (41,6%) were evaluated positively and 14 were evaluated negatively for the presence of MGMT promoter methylation." (PMID 36361838, 2022). "Analysis of MGMT promoter methylation as a biomarker was limited, as sufficient DNA was available in only 32 of 104 tumor samples." (PMID 35677534, 2022). "Overexpression of O6-methylguanine-DNA methyltransferase (MGMT) or mismatch repair (MMR) deficiency leads to rapid acquired TMZ resistance for GBM, which is a significant contributor to tumor recurrence." (PMID 35401877, 2022). "On the other hand, some studies reporting on the benefits of long-term treatment with TMZ have also indicated that prognosis varies depending on tumor MGMT promoter methylation status." (PMID 34320929, 2021). "MGMT is an important downstream signaling molecule for NF‐κB participation in drug resistance of malignant tumor cells." (PMID 33460245, 2021). "The better tumor segmentation and MGMT prediction performance both came from Fluid-attenuated inversion recovery (FLAIR) images." (PMID 34295824, 2021). "This is important from a potential clinical benefit point of view given that around half of these tumours are MGMT +ve and around half are MGMT −ve." (PMID 33668183, 2021). "MGMT promoter methylation enables the prediction of benefit from alkylating agents in patients with these tumours." (PMID 33293629, 2021). "MGMT promoter methylation was detected in 54/132 tumours (41%), including 23/74 tumours (31%) in the group of patients aged < 65y and 31/58 tumours (53%) in the elderly patient group." (PMID 32748120, 2021). "Long-term TMZ administration will minimize MGMT levels and weaken tumor cell resistance, thereby “autonomously” enhancing anti-tumor effects of TMZ." (PMID 34724914, 2021). "Unfortunately, tumor drug resistance is common, accomplished by increasing methylguanine-DNA-methyltransferase (MGMT) expression by demethylating its promoter site." (PMID 34452156, 2021). "Higher risk scores demonstrated stronger associative trends with older age, higher tumor grade, wild‐type (WT) IDH, 1p19q non‐codeletion (non‐codel), and non‐methylation of the MGMT promoter." (PMID 33459509, 2021). "Another downside is the tumor expression of DNA repair enzymes, such as MGMT, which nullify the alkylating agents’ therapeutic effects." (PMID 33803885, 2021). "ROC-derived cutoffs of 31 months of initiation of TMZ therapy, low-to-intermediate MGMT positivity (40% tumor cells), and MGMT h-score of 80 all had a sensitivity of at least 80% and a specificity of at least 70% to predict response." (PMID 34975752, 2021). "An nCounter platform allowed quantitative comparisons of antibodies between ROIs in MGMT methylated and unmethylated tumours." (PMID 33995529, 2021).
tumor (continued). "This suggests that MGMT-positive tumor cells become resistant to chemotherapy, and therefore would possess a depolarized Vm due to its proliferative state." (PMID 33758290, 2021). "Further, 19/20 co-gain also nullified the MGMT unmethylated tumor’s tendency to demonstrate pial invasion." (PMID 34199376, 2021). "In conclusion, WVRT significantly reduced the intraventricular failure rate in patients with GBMs involving the ventricle who had ventricles exposed during maximal tumor resection, especially in MGMT-unmethylated GBMs." (PMID 34621677, 2021). "Chemo-resistance in patients who do not respond to TMZ is mainly caused by the expression and activity of the DNA repair enzyme MGMT, which removes the chemotherapy-induced methyl group, thus preventing the DNA damage that leads to tumor cell death." (PMID 34646647, 2021). "The correlation between the risk model, the cluster model, tumor grade, IDH status, 1p19q status, and MGMT status was analyzed and displayed by the Sankey diagram." (PMID 34603309, 2021). "The proposed radiomic model reliably predicted MGMT status from MRI contrast enhancing tumor regions after intensity normalization with linear interpolation in an independent cohort." (PMID 33937035, 2021). "Among patients with IDH mutant tumours, 1p/19q codeleted tumours had greater signal heterogeneity (P = 0.002) and lower EC (P = 0.005), and MGMT-methylated tumours showed lower EC (P = 0.03)." (PMID 33958734, 2021). "The outcome of these low MGMT cases varies, including cases of complete regression, partial regression, and stabilization of the tumor." (PMID 33841328, 2021). "Lower expression of MGMT has been suggested to increase tumour sensitivity to Temozolomide, which is frequently used for treatment of advanced PanNETs." (PMID 33536587, 2021). "Nonetheless, by adjusting our analytic model, we addressed these limitations where possible, showing the MGMT status of the tumor and 5-ALA-GS as the only factors related to an improvement in the overall survival, rather than, for example, the use of IONM." (PMID 34131646, 2021). "In particular, in our cohort, checkpoint biomarker PD-L1 is statistically increased in MGMT methylated tumour cores compared with unmethylated tumour cores of GBMs (p = 0.025)." (PMID 33995529, 2021). "What’s more, the signature-based stratification was observed to be correlated with extensive clinical characteristics, including tumor grade, MGMT promoter methylation status, 1p19q-codeletion status, and IDH mutation status." (PMID 34950662, 2021). "Extent of resection and the O6-methylguanine-DNA methyltransferase (MGMT) promoter methylation status were determined for each tumour." (PMID 32748120, 2021). "The methylation status of the MGMT gene promoter has been considered as a crucial biomarker of tumor response to TMZ chemotherapy." (PMID 34295824, 2021). "To better understand the differences between tumours with POLE mutations and the other subtypes, we evaluated the methylation status of discrete regions within the promoter of the MGMT and SFRP2 genes." (PMID 34034807, 2021). "Here, we utilized data from a large number of GBM samples from multiple publicly available datasets to comprehensively investigate the potential relationship between MGMT status and the immunological tumor microenvironment." (PMID 33614641, 2021). "In this model, only tumor volume (HR: 1.02, 95% CI: 1.01–1.04, P = .0007) and MGMT status (HR: 0.35, 95% CI: 0.13–0.97, P = .044) were statistically significant." (PMID 34988455, 2021). "In summary, our study revealed that MGMT promoter methylation status is correlated with immunological processes and the remodeling of the tumor microenvironment in GBM." (PMID 33614641, 2021).
tumor (continued). "Age at diagnosis, KPS, MGMT promoter methylation and location of tumor were common significant predictors of survival for both sexes." (PMID 34761331, 2021). "MGMT promoter methylation correlates with improved tumor progression-free survival in patients treated with TMZ." (PMID 33661424, 2021). "When each group was subclassified by MGMT promotor methylation status however, the two groups showed different imaging features in a number of additional ways including tumor location, size, and ependymal extension." (PMID 34199376, 2021). "Patients with MGMT-methylated tumor had significantly higher Mg values and PME/PDE ratios, while their PCr/ATP and PCr/Pi ratios were lower than in patients without MGMT methylation." (PMID 34298788, 2021). "Patients with unmethylated MGMT and IDH1 mutation, treated with different chemoradiotherapies, showed a late tumor recurrence." (PMID 34257620, 2021). "Methylation of MGMT inhibits the function of this protein, thereby make the tumor sensitive to temozolomide." (PMID 33777772, 2021). "Since high levels of MGMT in tumor cells result in severe resistance to guanine O6-alkylating agents, a series of methyltriazene hybrids bearing DNA methylating triazenes and O6-BG was obtained." (PMID 33946916, 2021). "A similar effect was also noted upon the inhibition of Hh-GLI1 in mice GBM xenografts, whereby concurrent treatment with cyclopamine and TMZ significantly inhibited their MGMT expression and tumor burden compared to TMZ alone." (PMID 34638233, 2021). "This study, and others, based on bulk tumour or single-cell sequencing have identified molecular markers such as, methylation status of MGMT promoter and w/t IDH-1 status that have been widely explored as prognostic biomarkers for therapy responsiveness." (PMID 34490102, 2021). "Previous findings showed that MGMT regulates angiogenesis in tumor cells by changing the levels of different vascular endothelial growth factor receptors." (PMID 34814870, 2021). "MGMT tumor methylation was also positively correlated to increased treatment response (51.6% vs. 14.0%), which is in line with the recent literature." (PMID 34185258, 2021). "MGMT inactivation predisposes to alkylation-induced DNA damage, which is associated with G → A transition mutations in the KRAS oncogene, thus driving tumor growth." (PMID 33978766, 2021). "Even after incomplete resection, patients with MGMT hypermethylated tumor demonstrated increased OS and PFS." (PMID 34185258, 2021). "The DNA repair enzyme O6-methylguanine-DNA methyltransferase (MGMT) inhibits the killing of tumor cells by TMZ." (PMID 33442407, 2021). "In patients with a high edema to tumor ratio, the MGMT promotor was methylated (+) in 38 patients (53%) and in 30 patients (42%) of the low edema to tumor ratio cohort (p=0.40; 95%CI: 0.36-1.37; OR: 07)." (PMID 33868245, 2021). "Of note, higher CAFs (AUC = 0.7994), tumor histology (AUC = 0.7822), IDH status (AUC = 0.8066), 1p/19q status (AUC = 0.8163) and MGMT promotor status (AUC = 0.5641) was shown in the high-risk group than in the lower group." (PMID 34778248, 2021). "Tumours in the T2 subgroup had lower methylation in CpGs located in the body of MGMT gene, which showed positive correlation with gene expression." (PMID 33536587, 2021). "NPC xenograft studies demonstrated that MGMT inhibition combined with CDDP treatment reduced tumor size and downregulated RAD51 expression and BRCA1 phosphorylation." (PMID 33397362, 2021). "O6‐methylguanine‐DNA methyltransferase (MGMT) is a DNA repair protein that repairs the damage inflicted by alkylating agents (such as TMZ) upon tumor cell DNA and thus imparts resistance to alkylating agents in tumor cells." (PMID 33460245, 2021). "MGMT gene silencing due to promotor methylation makes the affected tumor cells more sensitive to alkylating chemotherapeutics and leads to an increased overall survival in case of GBM." (PMID 33857203, 2021).
tumor (continued). "Tumor MGMT promoter methylation status was obtained from the medical records of 59 patients, showing that almost half of these tumors displayed an un-methylated MGMT promoter (28/59)." (PMID 34577582, 2021). "Temozolomide as an alkylating and methylating agent has been reported to be certainly less effective in patients with MGMT unmethylated tumor." (PMID 33959183, 2021). "In this study, we aimed to evaluate the combined effect of MGMT methylation and tumor vascularity on patient survival, assessing the performance of the proposed rCBV threshold for patient stratification." (PMID 34771583, 2021). "It is proposed that tumor sensitivity to temozolomide is dependent of the levels of DNA repair enzyme O6-methylguanine DNA methyltransferase (MGMT)." (PMID 35008293, 2021). "The assessment of the SSTR, PD-L-1 and MGMT status in tumour tissue will provide the mechanistic basis for recommending more targeted therapies, resulting in more personalised and cost-effective treatments." (PMID 34681905, 2021). "On average, tumor progression in MGMT promoter methylated residual tumors was diagnosed 0.41 months later than patients with an unmethylated MGMT promoter." (PMID 34185258, 2021). "In our cohort, PD-L1 expression is statistically increased in MGMT methylated tumour cores compared with unmethylated tumour cores of GBMs (p = 0.025)." (PMID 33995529, 2021). "We observed a statistically significant difference in FOXP3 (p = 0.03) between MGMT methylated and unmethylated tumour core, although overall counts are low (MGMTuc = 7.02 [0.51] and MGMTmc = 7.94 [0.73])." (PMID 33995529, 2021). "TMZ is effective if the tumor lacks MGMT or expresses the repair protein at a low level, supporting the notion that MGMT is an important prognostic marker." (PMID 34944906, 2021). "The epigenetic silencing of DAPK, along with RARβ2, RASSF1A, and MGMT, has been observed as a common mechanism of tumor formation in cutaneous melanoma." (PMID 34944843, 2021). "There was also a high proportion of incomplete information regarding tumor mutations and biomarkers, including IDH mutation status and MGMT promoter methylation status." (PMID 34355171, 2021). "We also noted a statistical increase of B7-H3 in MGMT methylated tumour core B7-H3 (CD276) against MGMT unmethylated tumour core (p = 0.023)." (PMID 33995529, 2021). "For example, we found indices of faster cell reproduction and tumor growth in MGMT-methylated and EGFR-amplified tumors." (PMID 34298788, 2021). "The authors described the progressive shift of the tumor (at his 3rd recurrence) from epithelioid to classic GBM pattern, with loss of MGMT methylation and related intense fluorescence expression after 5-ALA administration." (PMID 34208653, 2021). "Patients with MGMT-methylated tumor had significantly higher Mg values (p = 0.01) and PME/PDE ratio (p < 0.0001), while their PCr/ATP (p = 0.03) and PCr/Pi (p = 0.04) ratios were lower." (PMID 34298788, 2021). "The use of MGMT inhibitors is limited by their hematological toxicity; therefore, another strategy has been to deplete MGMT activity in tumor tissue using a dose-dense temozolomide schedule." (PMID 33661424, 2021). "In GBM, the overexpression of the ZEB1 gene induced the expression of MGMT, resulting in greater tumor chemoresistance and also induced the expression of SOX2 and OLIG2, resulting in greater stemness and higher capacity for tumor formation." (PMID 33762015, 2021). "In GBM, MGMT promoter methylation status is an essential determinant of the aggressiveness of the tumor." (PMID 33614641, 2021). "We addressed the critical role of MGMT methylation in regulating the remodeling of the tumor microenvironment of GBM." (PMID 33614641, 2021). "Based on the AIC criteria, age at diagnosis, KPS, MGMT status and location of tumor were common significant predictors of survival for both sexes." (PMID 34761331, 2021).